CYFIP2 (cytoplasmic FMR1 interacting protein 2)
Description:
Does not bind RNA. As component of the WAVE1 complex, required for BDNF-NTRK2 endocytic trafficking and signaling from early endosomes (By similarity).
Synonyms: PIR121; DEE65; EIEE65
Tractability: PROTAC: ubiquitination databases record sites on it; its protein half-life has been measured.
Gene: Protein-coding gene on chromosome 5 (157,266,079 to 157,395,595, forward strand). Ensembl gene ENSG00000055163.
Subcellular location: Cytoplasm; Nucleus; Cytoplasm, perinuclear region; Synapse, synaptosome
Subcellular location (Human Protein Atlas): Endoplasmic reticulum; Cytosol; Plasma membrane
Pathways (Reactome):
Signal Transduction: RAC1 GTPase cycle; RHO GTPases Activate WASPs and WAVEs; VEGFA-VEGFR2 Pathway
Disease: FCGR3A-mediated phagocytosis
Immune System: Regulation of actin dynamics for phagocytic cup formation
Gene Ontology:
Molecular function: protein binding; RNA 7-methylguanosine cap binding; small GTPase binding
Biological process: apoptotic process; cell-cell adhesion; positive regulation of proteolysis; regulation of postsynapse assembly; axon guidance; dendrite extension; neuron projection development; positive regulation of neurotrophin TRK receptor signaling pathway; regulation of actin filament polymerization
Cellular component: cytoplasm; cytosol; extracellular exosome; membrane; nucleus; perinuclear region of cytoplasm; SCAR complex; synapse; neuron projection
Genetic constraint (gnomAD): Loss-of-function variants: 29 observed, 144.48 expected, observed/expected ratio (o/e) 0.2, 90% interval 0.15 to 0.27. The upper end of that interval is the gene's LOEUF score, 0.27, which puts it in group 1 of 6, group 1 being the genes least tolerant of losing a copy. Missense variants: 824 observed, 1,579.1 expected, observed/expected ratio (o/e) 0.52, 90% interval 0.49 to 0.55. Synonymous variants: 571 observed, 604.75 expected, observed/expected ratio (o/e) 0.94, 90% interval 0.88 to 1.01.
Gene-disease validity (ClinGen):
ClinGen rates the evidence that CYFIP2 causes each of these diseases.
complex neurodevelopmental disorder (autosomal dominant): Definitive. A disorder that involves more than one phenotype associated with the central nervous system, including but not limited to intellectual disability, autism, and seizures (epilepsy).
Homologues: Orthologues: chimpanzee CYFIP2 (100% identical), macaque CYFIP2 (100% identical), pig CYFIP2 (100% identical), rabbit CYFIP2 (100% identical), dog CYFIP2 (99% identical), mouse Cyfip2 (99% identical), rat Cyfip2 (99% identical), tropical clawed frog cyfip2 (98% identical), zebrafish cyfip2 (98% identical), guinea pig CYFIP2 (97% identical), Drosophila melanogaster Cyfip (67% identical), Caenorhabditis elegans gex-2 (52% identical). Paralogues in human: CYFIP1 (88% identical).
Diseases named in the same sentence as CYFIP2 in open-access papers:
CYFIP2 is named in the same sentence as 78 diseases in open-access papers, as found by Europe PMC text mining. Sharing a sentence is not in itself a finding about the gene and the disease. The quoted sentences say what the papers report.
Epileptic encephalopathy (8 papers, 2018 to 2026). A condition in which epileptiform abnormalities are believed to contribute to the progressive disturbance in cerebral function. "Mutations in the CYFIP2 gene, particularly the R87C variant, are associated with severe epileptic encephalopathy, and present challenges for therapeutic development." (PMID 41851324, 2026). "Haploinsufficiency of Cyfip2 in mice caused developmental and epileptic encephalopathy, including microcephaly and abnormal social behaviors, such as increased anxiety." (PMID 40481608, 2025). "CYFIP2 was recently correlated to neurological disorders by the association of the R87C variant with early infantile epileptic encephalopathy (EIEE) patients." (PMID 35955843, 2022). "Early infantile epileptic encephalopathy (EIEE) 65 was recently shown to be caused by the cytoplasmic FMRP interacting protein 2 (CYFIP2) mutation." (PMID 31689829, 2019). "Recent whole exome sequencing studies identified de novo hotspot variants in CYFIP2 from patients with early-onset epileptic encephalopathy and microcephaly, suggesting that CYFIP2 may have some functions in embryonic brain development." (PMID 30687000, 2018). "Together, our results suggest that the CYFIP2 R87C variant impacts NPC cytoskeletal dynamics and early cortical development, warranting further investigation into its role in epileptic encephalopathy." (PMID 41851324, 2026). "CYFIP2 is a component of the actin regulatory WAVE complex, which binds the fragile X messenger ribonucleoprotein (FMRP) and has been implicated in developmental delay, epilepsy, West syndrome (a developmental and epileptic encephalopathy), and Alzheimer’s disease." (PMID 38516548, 2023).
Intellectual disability (8 papers, 2020 to 2023). "De novo variants in CYFIP2 have been reported to cause intellectual disability, seizures, and early-onset epileptic encephalopathy." (PMID 35664469, 2022). "The cytoplasmic fragile X mental retardation 1 (FMR1)-interacting protein 2 (CYFIP2) gene is associated with epilepsy, intellectual disability (ID), and developmental delay, suggesting its critical role in proper neuronal development and function." (PMID 33192297, 2020). "In this study, we systematically analyzed CYFIP2 mutations, reported to cause intellectual disability." (PMID 32486060, 2020). "Specifically, in the case of CYFIP2, de novo variants have recently been identified in individuals diagnosed with neurodevelopmental disorders and early-onset epileptic encephalopathy characterized by developmental regression, intellectual disability, seizures, muscular hypotonia, and microcephaly." (PMID 36999135, 2023). "Importantly, both CYFIP1 and CYFIP2 genes are associated with various types of brain disorders, including autism spectrum disorders, intellectual disability, schizophrenia, and epilepsy, suggesting critical roles of CYFIP1 and CYFIP2 in proper brain development and function." (PMID 32917241, 2020). "CYFIP2 is another member of the CYFIP family that was associated with Alzheimer’s disease, intellectual disability, and early-onset epileptic encephalopathy." (PMID 36036011, 2022). "Recently, two independent studies described de novo mutations in the CYFIP2 subunit of WRC, which caused intellectual disability (ID) in humans." (PMID 32486060, 2020). "CYFIP2 belongs to the CYFIP family which has been related to autism and intellectual disability." (PMID 37033658, 2023).
gastric cancer (7 papers, 2017 to 2023). A primary or metastatic malignant neoplasm involving the stomach. "Circulating CYFIP2 was demonstrated to be significantly upregulated in gastric cancer tissues and cell lines and high expression of circulating CYFIP2 was associated with metastasis and poor prognosis of gastric cancer patients." (PMID 37735711, 2023). "It has been reported that inhibition of CYFIP2 increased cell growth and resistance to chemotherapy in gastric cancer through activating the Akt signal." (PMID 35614925, 2022). "In gastric cancer cells, CYFIP2 silencing resulted in enhanced proliferation and colony formation, decreased apoptosis and induced resistance to 5-FU." (PMID 29287594, 2017). "Additionally, it was revealed that miR-1205 repressed the proliferation and invasion of gastric cancer cells through interaction with circRNA cytoplasmic FMR1 interacting protein 2 (circCYFIP2)." (PMID 34127015, 2021).
Alzheimer disease (6 papers, 2016 to 2023). A progressive, neurodegenerative disease characterized by loss of function and death of nerve cells in several areas of the brain leading to loss of cognitive function such as memory and language. "Beyond the genetic association between CYFIP2 and neurodevelopmental disorders, recent studies have suggested a mechanistic association between the reduction of CYFIP2 and Alzheimer's disease (AD)." (PMID 36999135, 2023). "In any case, it is intriguing that reduced CYFIP2 expression links together spatial memory loss with amyloid production and tau hyperphosphorylation, three features and hallmarks of Alzheimer’s disease." (PMID 27524794, 2016). "Tiwariet al. reveal reduced CYFIP2 expression in post-mortem Alzheimer’s disease brains, and show that CYFIP2 reduction in mice causes abnormal amyloid production, tau hyperphosphorylation, and spatial memory loss." (PMID 27524794, 2016). "Therefore, reduced CYFIP2 expression in severe Alzheimer’s disease might be due to synapse loss that occurs before neuronal loss." (PMID 27524794, 2016). "CYFIP2 protein expression is significantly reduced in Alzheimer’s disease cases, and cognitive behavioral tests showed that reduced CYFIP2 expression prevents mice from being able to solve the water maze by affecting body spatial memory function." (PMID 37645701, 2023). "We investigated if the reduced CYFIP2 expression observed in post-mortem Alzheimer’s disease brain can also be found in a mouse model of a familial form of the disease." (PMID 27524794, 2016). "CYFIP2 expression was found to be significantly downregulated in severe Alzheimer’s disease STG (t= −3.28,P< 0.01), supporting our finding of reduced CYFIP2 expression in the hippocampus." (PMID 27524794, 2016). "Taken together, our findings indicate that reduced CYFIP2 expression triggers a cascade of change towards Alzheimer’s disease, including amyloid production, tau hyperphosphorylation and memory loss." (PMID 27524794, 2016). "Reduced CYFIP2 expression by ∼50% in 12-month-old Tg2576 mice resembles the reduced CYFIP2 expression in post-mortem Alzheimer’s disease forebrain." (PMID 27524794, 2016). "We suggest that CYFIP2 expression decreases already in the early stages of Alzheimer’s disease, as we found an ∼2-fold reduction in mild Alzheimer’s disease hippocampus (Braak stages I–II)." (PMID 27524794, 2016). "The decreased, normalized CYFIP2 expression in post-mortem Alzheimer’s disease forebrain indicates that CYFIP2 levels decline before neurons and synapses die." (PMID 27524794, 2016). "We found that CYFIP2 expression was significantly reduced by ∼40% in hippocampus of late Alzheimer’s disease (Braak stages V–VI) in comparison to expression in control subjects (t= −2.33;P< 0.05; seeSupplementary material)." (PMID 27524794, 2016). "There appeared to be an upregulation in CYFIP1 levels in severe Alzheimer’s disease hippocampus (t= 3.27,P< 0.01), contrary to the significant downregulation of CYFIP2 expression." (PMID 27524794, 2016). "This suggests that there are molecular ‘hubs’ that contribute to various aspects of Alzheimer’s disease, and that reduced CYFIP2 expression is one of these." (PMID 27524794, 2016). "We found that CYFIP2/synaptophysin expression was significantly decreased by ∼40% in severe Alzheimer’s disease hippocampus (t= 2.43; P< 0.05), suggesting that CYFIP2 expression declines before synapse loss occurs." (PMID 27524794, 2016). "Notably, a few recent studies have also suggested a mechanistic link between reduced CYFIP2 level and Alzheimer's disease (AD)." (PMID 36999135, 2023). "CYFIP2 could represent a molecular ‘hub’ with potential as a therapeutic target in Alzheimer’s disease." (PMID 27524794, 2016). "Our previous studies on p25 dysregulation put forward the hypothesis that CYFIP2 expression is reduced in Alzheimer’s disease and that this contributes to memory impairment, abnormal APP processing and tau hyperphosphorylation." (PMID 27524794, 2016).
Alzheimer disease (continued). "To assure that CYFIP2 expression is not simply reduced due to neuronal and synaptic loss in Alzheimer’s disease, we normalized CYFIP2 levels to expression of a neuronal housekeeping protein as well as to a synaptic vesicle protein." (PMID 27524794, 2016). "Our previous studies on p25 dysregulation suggested that CYFIP2 expression could be reduced in Alzheimer’s disease (Engmannet al., 2011)." (PMID 27524794, 2016). "Applied to Alzheimer’s disease this could suggest that genetic modifiers may suppress the impact of reduced CYFIP2 expression on amyloid production, tau hyperphosphorylation and spatial memory loss in some patients." (PMID 27524794, 2016). "Here, we show that expression of CYFIP2 protein is substantially reduced in Alzheimer’s disease forebrain and our functional studies in mice suggest that this CYFIP2 downregulation links together amyloid production, tau hyperphosphorylation and spatial memory loss." (PMID 27524794, 2016). "As CYFIP1 has similar functionsin vitroto CYFIP2, we wanted to know if CYFIP1 could be implicated in mild stages of Alzheimer’s disease." (PMID 27524794, 2016). "Alternatively, reduced CYFIP2 expression may occur before synapses die in Alzheimer’s disease." (PMID 27524794, 2016). "Therefore, we hypothesized that in early Alzheimer’s disease CYFIP2 expression is reduced and this would contribute to synaptic degeneration." (PMID 27524794, 2016). "Therefore, we suggest that CYFIP2 could be one of the key targets for prevention of Alzheimer’s disease." (PMID 27524794, 2016). "Therefore, we studied whether not only CYFIP2 expression but also FMRP expression would be altered in severe Alzheimer’s disease hippocampus." (PMID 27524794, 2016). "We also studied CYFIP2 expression in the STG, which is affected to a lesser extent and at later stages than the hippocampus in Alzheimer’s disease." (PMID 27524794, 2016). "Consistent with this idea, we found that CYFIP2 protein expression is reduced in an APP transgenic mouse line, the Tg2576 mouse, which models early Alzheimer’s disease (Hsiaoet al., 1996;Stewartet al., 2011)." (PMID 27524794, 2016). "Here, we tested this hypothesis by analysing CYFIP2 and CYFIP1 expression in post-mortem Alzheimer’s disease brain tissue." (PMID 27524794, 2016). "There was also no change of CYFIP1 expression in STG tissues from patients with severe Alzheimer’s disease (t= −1.15,P= 0.26), as opposed to CYFIP2 reduction seen in severe Alzheimer’s disease STG." (PMID 27524794, 2016). "In contrast to CYFIP2 expression, the level of CYFIP1 expression is not changed in post-mortem Alzheimer’s disease brain, with the exception that CYFIP1 expression is elevated in severe Alzheimer’s disease hippocampus." (PMID 27524794, 2016).
autism (6 papers, 2016 to 2025). Persistent deficits in social interaction and communication and interaction as well as a markedly restricted repertoire of activity and interest as well as repetitive patterns of behavior. "The expression of CYFIP2 is changed in autism and fragile X syndrome." (PMID 35664469, 2022). "It is important to note that Cytoplasmic FMR1-interacting protein 2 (CYFIP2) was identified as an interaction of FMRP, clearly related to Autism." (PMID 26947246, 2016). "Thus, reduced CYFIP2 expression might not cause any neurodevelopmental abnormalities that lead to autism-like behaviours." (PMID 27524794, 2016). "We studied whether reduced CYFIP2 expression inCyfip2+/−mice affects social behaviour in the three-chamber task and repetitive behaviour in the marble burrowing task, two behaviours that are impaired in mouse models of autism (Silvermanet al., 2010;Santiniet al., 2013)." (PMID 27524794, 2016).
epilepsy (5 papers, 2020 to 2025). A brain disorder characterized by episodes of abnormally increased neuronal discharge resulting in transient episodes of sensory or motor neurological dysfunction, or psychic dysfunction. "Analysis of a whole exome sequencing (WES) based multigene panel for epilepsy disclosed a heterozygous CYFIP2 gene variant [c.258_266del; p.(Trp86_Ser88del)] established as de novo." (PMID 36968925, 2023).
colon cancer (4 papers, 2018 to 2022).
developmental delay (4 papers, 2020 to 2024). "Large chromosomal deletions harboring CYFIP2 have been identified in patients with developmental delay, ID, and seizures." (PMID 33192297, 2020).
fragile X syndrome (4 papers, 2017 to 2022). A genetic syndrome caused by mutations in the FMR1 gene which is responsible for the expression of the fragile X mental retardation 1 protein. "CYFIP2 is a member of a highly conserved gene family that has been genetically linked to autism spectrum disorder (ASD) and the Fragile X syndrome (FXS), the most common form of inherited intellectual disability." (PMID 29518358, 2018).
melanoma (4 papers, 2011 to 2022). A malignant, usually aggressive tumor composed of atypical, neoplastic melanocytes. "As a model system to systematically analyze the molecular consequences of CYFIP2 mutations normally occurring in neurodevelopmental disorders, we focused on B16-F1 mouse melanoma cells, in which the CYFIP1 and CYFIP2 genes were disrupted using CRISPR/Cas9." (PMID 32486060, 2020). "RNAi of CyFIP2 in murine melanoma cells leads to aberrant lamellipodia proving the functionality of Cyfip2 in actin remodeling and cell motility." (PMID 22787438, 2012).
Anxiety (3 papers, 2020 to 2025). Intense feelings of nervousness, tension, or panic often arise in response to interpersonal stresses. "Cyfip2 mutations in mice have been reported to regulate cocaine response and Fragile X-like behaviors including increased anxiety-like behavior, decreased startle response, and enhanced prepulse inhibition." (PMID 35664469, 2022). "Unexpectedly, adult Cyfip2 cKO mice did not display locomotor hyperactivity or reduced anxiety observed in Cyfip2+/− mice." (PMID 33192297, 2020).
asthma (3 papers, 2009 to 2022). "Actually, the associations of ADAM33, NPSR1, and CYFIP2 with asthma or asthma-related phenotypes have been studied in Chinese or Japanese populations." (PMID 19951440, 2009). "For ADAM33, NPSR1, and CYFIP2, the associations with asthma or asthma-related phenotypes have been studied in East Asian populations such as Chinese and Japanese." (PMID 19951440, 2009). "Six asthma candidate genes, ADAM33, NPSR1, PHF11, DPP10, HLA-G, and CYFIP2, located at different chromosome regions have been positionally cloned following the reported linkage studies." (PMID 19951440, 2009).
Early Infantile Epileptic Encephalopathy (3 papers, 2019 to 2022). "All 5 of the cases of early-onset EE reported with CYFIP2 mutations were primarily diagnosed as Ohtahara syndrome (n = 2) or West syndrome (n = 3)." (PMID 31689829, 2019).